HTRA1 (HtrA serine peptidase 1)
Diseases named in the same sentence as HTRA1 in open-access papers (continued):
Sharing a sentence is not in itself a finding about the gene and the disease.
dilated cardiomyopathy (4 papers, 2024 to 2026). Cardiomyopathy which is characterized by dilation and contractile dysfunction of the left and right ventricles. "HTRA1, another cluster 3-specific candidate encoding a serine protease, facilitates collagen detachment from ER and contributes to myocardial fibrosis in dilated cardiomyopathy." (PMID 41547928, 2026). "Increased HTRA1 expression has been identified in patients with dilated cardiomyopathy and is strongly correlated with fibrosis." (PMID 40704293, 2025).
macular degeneration (4 papers, 2013 to 2025). Loss of vision in the central portion of the retina (macula), secondary to retinal degeneration. "Because of the retinal abnormalities detected in Htra1–/– mice, additional markers associated with dysregulated pathways observed in macular degenerations such as AMD were used to assess the repercussions of Htra1 loss on the retina, RPE, and choroid." (PMID 39927462, 2025). "Finally, the HTRA1-625A/G variant was associated with a decreased response to bevacizumab in people with macular degeneration (AA vs. GG; p = 0.006)." (PMID 33198211, 2020). "All of these findings in the Htra1–/– model are consistent with biological processes that are known to play a role in macular degeneration, including AMD." (PMID 39927462, 2025). "A role for HtrA1 in cell proliferation has been described in a small number of studies for conditions such as macular degeneration and skeletal osteoarthritis." (PMID 26035313, 2015). "Thus, the ablation of Htra1 affects overall retina and RPE integrity, and it recapitulates distinct pathological features observed in macular degeneration." (PMID 39927462, 2025). "Anti-VEGF drugs have been related to variable response depending on CXCL8, VEGFA, NRP1, ARMS2, CFH, and HTRA1 genotypes in macular degeneration and depending on VEGFA genotype in CNV patients, without differentiating results among PCV patients." (PMID 33198211, 2020).
Myocardial fibrosis (4 papers, 2023 to 2026). "The findings of this study provide valuable insights regarding the treatment of DCM-associated myocardial fibrosis and highlight the therapeutic potential of targeting HTRA1-mediated collagen secretion." (PMID 38515161, 2024). "Furthermore, a Pearson correlation analysis demonstrated a significant positive correlation between HTRA1 expression and key molecules associated with myocardial fibrosis, such as Col1, α-SMA, and CTGF." (PMID 38515161, 2024). "Although this study extensively investigated the molecular mechanisms of HTRA1 in myocardial fibrosis, some limitations remain." (PMID 38515161, 2024). "Herein, we discovered that the HtrA serine peptidase 1 (HTRA1) level was considerably increased in DCM, and it was strongly associated with myocardial fibrosis." (PMID 38515161, 2024). "In vivo experiments using adeno-associated virus-serotype 9-shHTRA1-green fluorescent protein (AAV9-shHTRA1-GFP) showed that HTRA1 knockdown effectively suppressed myocardial fibrosis and improved left ventricular function in mice with DCM." (PMID 38515161, 2024). "To investigate the potential of HTRA1 knockdown in ameliorating myocardial fibrosis in DCM mice, we utilized AAV9-shHTRA1-GFP to infect the heart tissue of C57BL/6 mice." (PMID 38515161, 2024). "These intriguing results strongly imply the substantial involvement of HTRA1 in the progression of myocardial fibrosis in DCM, thus warranting further comprehensive investigations." (PMID 38515161, 2024). "The findings of this study provide valuable insights regarding the therapeutic potential of targeting HTRA1-mediated collagen secretion for treating myocardial fibrosis in DCM." (PMID 38515161, 2024). "Oxidative and ER stress can induce HTRA1 upregulation in various diseases, both of which directly contribute to myocardial fibrosis." (PMID 38515161, 2024). "The apoptosis of cardiac fibroblasts in DCM can improve the level of myocardial fibrosis to some extent, and inhibiting HTRA1 will have a beneficial effect." (PMID 38515161, 2024). "Furthermore, our findings strongly suggest that targeting the rate-limiting steps in collagen secretion, such as HTRA1-mediated trafficking, can effectively alleviate DCM-associated myocardial fibrosis and improve cardiac function." (PMID 38515161, 2024). "Therefore, we consider HTRA1 a safe and ideal therapeutic target for treating DCM-associated myocardial fibrosis." (PMID 38515161, 2024). "We did not establish HTRA1-specific knockout mice for cardiac fibroblasts, which cannot completely rule out the possibility of the involvement of HTRA1 in other cardiac cells affecting the progression of DCM-associated myocardial fibrosis." (PMID 38515161, 2024). "Furthermore, HTRA1 knockdown alleviated myocardial fibrosis in mice with DCM." (PMID 38515161, 2024). "However, it is unclear whether HTRA1 mediates the involvement of TGF-β1 in myocardial fibrosis and myocardial remodeling in DCM." (PMID 37869159, 2023). "RNA-sequencing analysis revealed an increased HtrA serine peptidase 1 (HTRA1) expression in patients with DCM, which is strongly correlated with myocardial fibrosis." (PMID 38515161, 2024).
osteoporosis (4 papers, 2016 to 2024). A condition of reduced bone mass, with decreased cortical thickness and a decrease in the number and size of the trabeculae of cancellous bone (but normal chemical composition), resulting in increased fracture incidence. "Further understanding the role of HTRA1 in bone formation and bone resorption might help to develop HTRA1 a therapeutic target in bone metabolic diseases such as osteoporosis." (PMID 31867863, 2020). "Careful attention may be required to use such inhibitors of HtrA1 for patients with osteoporosis, because HtrA1 may be involved in other processes as well." (PMID 30854478, 2019). "Elevated SPP1, COL1A1 and NT5E proteins may be secreted from the pituitary tumor to directly target the skeletal system, with resultant osteoporosis, while downregulated HTRA1 and ANGPT1 may deregulate in bone formation and development." (PMID 27690016, 2016). "HtrA1 may be a novel target for drug discovery for bone diseases including osteoporosis." (PMID 30854478, 2019). "SPP1 signalling and COL1A1 signalling in osteoporosis were previously reported; and NT5E, HTRA1 and ANGPT1 signalling pathways reported here require further confirmation." (PMID 27690016, 2016). "Secreted phosphoprotein 1 (SPP1), collagen type I α 1 chain (COL1A1), 5′-nucleotidase ecto (NT5E), HtrA serine peptidase 1 (HTRA1) and angiopoietin 1 (ANGPT1) and their signalling pathways are shown to be involved in osteoporosis in CD patients." (PMID 27690016, 2016). "SPP1 (secreted phosphoprotein 1), COL1A1 (collagen type I α 1 chain), NT5E (5′-nucleotidase ecto), HTRA1 (HtrA serine peptidase 1) and ANGPT1 (angiopoietin 1) and their signalling pathways involving osteoporosis in CD patients are identified." (PMID 27690016, 2016). "Although the molecluar mechanism of NT5E, HTRA1 and ANGPT1 in osteoporosis has not been studied yet, the signaling pathways regulated by them are closely related to the signal pathways of bone development and formation." (PMID 27690016, 2016).
ovarian tumors (4 papers, 2010 to 2020). "Narkiewicz and co-workers assessed HtrA1 mRNA and protein in 98 women with various types of ovarian tumors (20 benign, 7 borderline, 44 malignant, and 8 Krukenberg tumors) or with healthy ovaries (n=19) using densitometry, which provided relative values of HtrA1 expression." (PMID 26035313, 2015).
pancreatic cancer (4 papers, 2018 to 2024). "This study aimed to explore the function of HtrA1 in pancreatic cancer cell growth and its underlying mechanism." (PMID 30484491, 2018). "Therefore, our current study aimed to explore the role of HtrA1 in the pathogenesis of pancreatic cancer as well as its potential underlying mechanism." (PMID 30484491, 2018). "On the contrary, transfection with HtrA1-specific siRNA significantly increased the Notch-1 transcripts in pancreatic cancer cells." (PMID 30484491, 2018). "In the present study, we found that the mRNA expression of HtrA1 was lower in pancreatic cancer tissue than in the adjacent normal tissue." (PMID 30484491, 2018). "We found that the suppressive function of HtrA1 on cell proliferation was abolished upon up-regulation of Notch-1 in pancreatic cancer cells." (PMID 30484491, 2018). "To verify the biological role of HtrA1 in pancreatic cancer, we performed CCK-8 and colony formation assays to determine the growth potential of PANC-1 and BXPC-3 cells." (PMID 30484491, 2018). "On the contrary, siRNA-mediated knockdown of HtrA1 promoted the growth potential of pancreatic cancer cells." (PMID 30484491, 2018). "We found that the expression of HtrA1 was lower in pancreatic cancer tissue compared to the adjacent normal tissue." (PMID 30484491, 2018). "In conclusion, the present study showed that HtrA1 inhibited the proliferation of pancreatic cancer cells by modulating Notch-1 expression." (PMID 30484491, 2018). "As a result, we found that forced expression of f HtrA1 inhibited the growth ability of pancreatic cancer cells." (PMID 30484491, 2018). "Taken together, these data suggested that the expression levels of HtrA1 were lower in pancreatic cancer." (PMID 30484491, 2018). "Consistently, HtrA1 levels were also decreased in two human pancreatic cancer cell lines, PANC-1 and BXPC-3." (PMID 30484491, 2018). "Consistently, the expression levels of HtrA1 were decreased in pancreatic cancer cells compared with those in the normal pancreatic epithelial cells." (PMID 30484491, 2018). "The pancreatic cancer PANC-1 cells were transfected with pcDNA3.1-HtrA1 plasmid to up-regulate the expression of HtrA1." (PMID 30484491, 2018). "In the current research, we found that enforced expression of HtrA1 suppressed Notch-1 expression in pancreatic cancer cells." (PMID 30484491, 2018). "In contrast, HtrA1-specific siRNA knockdown enhanced the expression levels of Notch-1 in pancreatic cancer cells." (PMID 30484491, 2018). "Collectively, our findings revealed that HtrA1 played a critical role in the proliferation of pancreatic cancer cells mediated by Notch-1." (PMID 30484491, 2018). "Collectively, these findings demonstrated that HtrA1 served as a tumor suppressor in pancreatic cancer cells." (PMID 30484491, 2018). "Subsequently, the expression of HtrA1 was detected in several human pancreatic cancer cell lines with the normal pancreatic epithelial cell line hTERT-HPNE used as control." (PMID 30484491, 2018). "The role of HtrA1 in the regulation of pancreatic cancer cell growth was further explored by CCK-8 assay." (PMID 30484491, 2018). "Thus, we used KC mice model to recapitulate PDAC initiation and investigated the effects of HTRA1 on pancreatic tumors in vivo." (PMID 38287020, 2024). "Therefore, our results pointed out that HtrA1 functioned as a tumor suppressor in pancreatic cancer cells." (PMID 30484491, 2018). "Taken together, our findings demonstrated that HtrA1 could inhibit pancreatic cancer cell growth via regulating Notch-1 expression, which implied that HtrA1 might be developed as a novel molecular target for pancreatic cancer therapy." (PMID 30484491, 2018). "Furthermore, overexpression of Notch-1 abolished the anti-proliferative effect of HtrA1 on pancreatic cancer cells." (PMID 30484491, 2018). "Our present study pointed out that HtrA1 could serve as a potential therapeutic target for pancreatic cancer treatment." (PMID 30484491, 2018).
pancreatic cancer (continued). "Consequently, we found that the HtrA1 transcripts and protein expression were also reduced in the pancreatic cancer cell lines PANC-1 and BXPC-3 compared with the normal pancreatic epithelial cell line hTERT-HPNE." (PMID 30484491, 2018). "Furthermore, we evaluated if HtrA1 played a role in the regulation of pancreatic cancer cells in a Notch-1-dependent manner." (PMID 30484491, 2018). "In addition, we found that up-regulation of HtrA1 reduced the expression of Notch-1 in pancreatic cancer cells." (PMID 30484491, 2018). "Our findings demonstrated that HtrA1 could serve as a potential therapeutic target for the treatment of pancreatic cancer." (PMID 30484491, 2018). "In addition, we found that overexpression of Notch-1 reversed the suppressive effect of HtrA1 on tumor cell growth, suggesting that the anti-proliferative ability of HtrA1 was dependent on Notch-1 in pancreatic cancer." (PMID 30484491, 2018). "Our findings could provide information on role of HtrA1 in the regulation of pancreatic cancer biological behaviors." (PMID 30484491, 2018). "We furthermore investigated the mechanism of HtrA1 in the proliferation of pancreatic cancer cells." (PMID 30484491, 2018). "Thus, we investigated the role of HtrA1 in regulating Notch signaling in pancreatic cancer cells." (PMID 30484491, 2018). "Hence, we examined whether HtrA1 levels were also reduced in pancreatic cancer." (PMID 30484491, 2018). "Real-time PCR and western blot analysis revealed that the mRNA and protein expression of HtrA1 was lower in pancreatic cancer tissue than the non-tumorous tissue." (PMID 30484491, 2018). "However, the expression and functional relevance of HtrA1 in pancreatic cancer has not been investigated." (PMID 30484491, 2018). "However, the expression profile and functional relevance of HtrA1 in pancreatic cancer has not been reported." (PMID 30484491, 2018).
retinal degeneration (4 papers, 2019 to 2025). Degeneration of the retina. "Next, we examined whether the observed retinal degeneration in HTRA1 WT transgenic mice is associated with reactive gliosis of microglia and Müller glia by use of IHC and flow cytometry." (PMID 40832922, 2025). "Thus, our data support that the age- and dosage-dependent retinal degeneration is caused by HTRA1 protease activity." (PMID 40832922, 2025). "However, assessment of the retinal layer thickness by optical coherence tomography (OCT) scanning and histology revealed that HTRA1 overexpression by the RPE cells caused retinal degeneration, which was dependent on transgene dosage and age of the animals." (PMID 40832922, 2025). "In conclusion, HTRA1 WT overexpression did not significantly exacerbate retinal degeneration triggered by phototoxic stress." (PMID 40832922, 2025). "According to the results in ARPE-19 cells that KC7F2 could reduce the HIF1α expression induced by HTRA1 and halt the cellular senescence, we explored whether KC7F2 could improve retinal degeneration induced by NaIO3in-vivo." (PMID 37316948, 2023). "Our study demonstrated that HTRA1 could activate HIF-1 signaling and promote RPE senescence in retinal degeneration." (PMID 37316948, 2023). "However, the relationship between HTRA1 and RPE senescence in retinal degeneration hasn’t been investigated." (PMID 37316948, 2023). "Using our transgenic mice, we showed that overexpression of protease active HTRA1 triggered spontaneous age-related photoreceptor degeneration; however, this retinal degeneration was not exacerbated when the mice were subjected to phototoxic stress under the CLE preclinical model." (PMID 40832922, 2025). "Finally, as substrate processing may define the molecular basis for HTRA1-induced retinal degeneration, we initiated a proteomics approach and identified the visual cycle key player RBP3 as a disease-relevant HTRA1 substrate in the retina." (PMID 40832922, 2025).
amyotrophic lateral sclerosis (3 papers, 2023 to 2025). Amyotrophic lateral sclerosis (ALS) is a neurodegenerative disease characterized by progressive muscular paralysis reflecting degeneration of motor neurons in the primary motor cortex, corticospinal tracts, brainstem and spinal cord. "Here, we report that HTRA1 inhibits aggregation of α-syn as well as FUS and TDP-43, which are implicated in amyotrophic lateral sclerosis (ALS) and frontotemporal dementia." (PMID 38499535, 2024). "Here the authors report that HTRA1 inhibits aggregation of α-syn as well as FUS and TDP-43, which are implicated in amyotrophic lateral sclerosis (ALS) and frontotemporal dementia." (PMID 38499535, 2024). "Here, we establish that HtrA1 inhibits the aggregation of α-syn as well as FUS and TDP-43, which are implicated in amyotrophic lateral sclerosis (ALS) and frontotemporal dementia (FTD)." (PMID 37674720, 2023).
cervical cancer (3 papers, 2021 to 2023). A primary or metastatic malignant neoplasm involving the cervix. "In cervical cancer, the overexpression of HTRA1 in the CaSki cell line promoted cell proliferation without interfering with the rate of apoptosis." (PMID 36992411, 2023).
choroidal neovascularization (3 papers, 2008 to 2025). An eye disorder described by the growth of new blood vessels that originate from the choroid through a break in the Bruch membrane into the sub–retinal pigment epithelium (sub-RPE) or subretinal space. "However, mice overexpressing catalytically active HTRA1 had significant exacerbation of laser-induced choroidal neovascularization lesions." (PMID 40832922, 2025).
colon carcinoma (3 papers, 2016 to 2021). "HTRA1 is epigenetically silenced in HCT116 colon carcinoma cells via the epigenetic adaptor protein MBD2." (PMID 27388476, 2016). "We show that HTRA1 is epigenetically silenced in HCT116 colon carcinoma cells and during early stages of tumorigenesis in a mouse model of intestinal cancer." (PMID 27388476, 2016). "In addition, the downregulation of HTRA1 also correlates with chemoresistance in colon cancer through the activation of the PI3K/AKT pathway." (PMID 34202399, 2021). "As HTRA1 is downregulated in a range of tumours we determined if silencing of HTRA1 occurs in cancer cell lines by analysing methylation of the HTRA1 promoter in two colon carcinoma cell lines (HCT116 and SW480)." (PMID 27388476, 2016). "In this cell line, exposure to TSA even reduced HTRA1 expression, which may be due to the side effect of TSA causing cell cycle arrest in colon carcinoma cells and fibroblasts." (PMID 27388476, 2016).